SLC6A7 (solute carrier family 6 member 7)
Description:
Brain specific sodium (and chloride)-dependent proline transporter. Terminates the action of proline by its high affinity sodium-dependent reuptake into presynaptic terminals (Probable).
Synonyms: PROT
Tractability: Small molecule: a high-quality ligand is known; it belongs to a druggable protein family. Antibody: UniProt places it where antibodies can reach, with high confidence; its Gene Ontology location is reachable by antibodies, with high confidence; UniProt predicts a signal peptide or a membrane-spanning region; the Human Protein Atlas places it where antibodies can reach. PROTAC: a small molecule that binds it is known.
Target class: SLC superfamily of solute carriers; SLC06 neurotransmitter transporter family; Electrochemical transporter; Transporter
Chemical probes: CHEMBL3318586 (high quality)
Gene: Protein-coding gene on chromosome 5 (150,190,062 to 150,222,788, forward strand). Ensembl gene ENSG00000011083.
Subcellular location: Synaptic cell membrane
Subcellular location (Human Protein Atlas): Cytosol; Plasma membrane
Pathways (Reactome):
Metabolism: Creatine metabolism
Transport of small molecules: SLC-mediated transport of neurotransmitters
Gene Ontology:
Molecular function: L-proline transmembrane transporter activity; proline:sodium symporter activity; transmembrane transporter activity
Biological process: proline transport; protein catabolic process; glycine import across plasma membrane; neurotransmitter transport; sodium ion transmembrane transport; proline transmembrane transport
Cellular component: synapse; synaptic membrane; membrane; plasma membrane
Genetic constraint (gnomAD): Loss-of-function variants: 56 observed, 68.9 expected, observed/expected ratio (o/e) 0.81, 90% interval 0.65 to 1.01. The upper end of that interval is the gene's LOEUF score, 1.01, which puts it in group 4 of 6, group 1 being the genes least tolerant of losing a copy. Missense variants: 762 observed, 837.99 expected, observed/expected ratio (o/e) 0.91, 90% interval 0.86 to 0.96. Synonymous variants: 325 observed, 338.94 expected, observed/expected ratio (o/e) 0.96, 90% interval 0.88 to 1.05.
Homologues: Orthologues: macaque SLC6A7 (99% identical), dog SLC6A7 (98% identical), rat Slc6a7 (98% identical), mouse Slc6a7 (98% identical), guinea pig SLC6A7 (97% identical), rabbit SLC6A7 (96% identical), chimpanzee SLC6A7 (96% identical), pig SLC6A7 (94% identical), tropical clawed frog slc6a7 (84% identical). Paralogues in human: SLC6A5 (49% identical), SLC6A9 (46% identical), SLC6A14 (44% identical), SLC6A13 (43% identical), SLC6A12 (42% identical), SLC6A11 (41% identical), SLC6A6 (40% identical), SLC6A8 (40% identical), SLC6A2 (39% identical), SLC6A3 (39% identical), SLC6A4 (38% identical), and 6 more.
Diseases named in the same sentence as SLC6A7 in open-access papers:
SLC6A7 is named in the same sentence as 26 diseases in open-access papers, as found by Europe PMC text mining. Sharing a sentence is not in itself a finding about the gene and the disease. The quoted sentences say what the papers report.
Atrophy (1 paper, 2022). Any weakening or degeneration, especially through lack of use. "Striatal atrophy and gliosis may be sequelae of status dystonicus with multiorgan failure, but the influence of mutant MPPE1 and SLC6A7 cannot be excluded." (PMID 35876425, 2022).
autism (1 paper, 2018). Persistent deficits in social interaction and communication and interaction as well as a markedly restricted repertoire of activity and interest as well as repetitive patterns of behavior. "Supporting this hypothesis, PROT mutations and Slc6A7 expression changes have been related to susceptibility to autism as well as schizophrenia, and microdeletions at the 5q32 locus containing the Slc6a7 gene have been associated with intellectual disability." (PMID 30177871, 2018).
movement disorder (1 paper, 2022). Neurological conditions resulting in abnormal voluntary or involuntary movement, which may impact the speed, fluency, quality and ease of movement. "In conclusion, we have identified variants in MED27, SLC6A7, and MPPE1 in a family with a complex and severe neurodevelopmental condition associated with a life‐threatening movement disorder." (PMID 35876425, 2022).
SLC6A7 also shares sentences with these, for which no sentence is quoted: tumor (3 papers); bladder cancer (2); cancer (2); infection (2); renal carcinoma (2); amnesia (1); bacteremia (1); bladder tumors (1); complex neurodevelopmental disorder (1); emphysema (1); epilepsy (1); hepatocellular carcinoma (1); hyperprolinemia (1); Intellectual disability (1); lung carcinoma (1); metastatic tumors (1); nasopharyngeal carcinoma (1); neurodegenerative disease (1); polycystic kidney disease (1); prostate carcinoma (1); schizophrenia (1); staphylococcus aureus infection (1); urothelial carcinoma (1).